CYSLTR1 (cysteinyl leukotriene receptor 1)
Diseases named in the same sentence as CYSLTR1 in open-access papers (continued):
Sharing a sentence is not in itself a finding about the gene and the disease.
inflammatory bone disease (1 paper, 2022). "To clarify the role of Cysltr1 in metabolic or inflammatory bone disease models, we performed ovariectomy in Cysltr1 KO female mice (OVX) or injected LPS into the calvaria of Cysltr1Δ105 mice." (PMID 36395281, 2022).
liver diseases (1 paper, 2020). "Recent studies suggested that CysLTR1 is also involved in various types of liver diseases." (PMID 32179525, 2020).
lung disease (1 paper, 2025). "This study expands our knowledge on the role of CysLTR1 beyond its role in immune regulation, that may later serve towards a better understanding of CysLTR1 associated lung diseases and in the development of improved therapeutic strategies." (PMID 41356350, 2025). "The cysteinyl leukotriene receptor 1 (CysLTR1) is known as a potent lipid mediator with a well-established role in inflammatory regulation and lung disease." (PMID 41356350, 2025). "This study serves as a basis towards a better understanding of the role of CysLTR1 in the lung, and many such studies to follow could be used towards inflammation related lung disease prevention or improved therapeutic strategies for such." (PMID 41356350, 2025).
obstructive sleep apnea (1 paper, 2021). "Human cysteinyl-leukotriene receptor-1 is markedly raised in the tonsillar tissue of youngsters with obstructive sleep apnea (OSA)." (PMID 33679914, 2021).
Osteopenia (1 paper, 2022). Osteopenia is a term to define bone density that is not normal but also not as low as osteoporosis. "Therefore, CysLTR1 alone may be excluded as a therapeutic target for diseases that cause osteopenia and bone destruction." (PMID 36395281, 2022).
osteoporosis (1 paper, 2022). A condition of reduced bone mass, with decreased cortical thickness and a decrease in the number and size of the trabeculae of cancellous bone (but normal chemical composition), resulting in increased fracture incidence. "Disruption of the Cysltr1 gene did not affect ovariectomy-induced osteoporosis or lipopolysaccharide-induced bone resorption." (PMID 36395281, 2022).
psoriasis (1 paper, 2024). An autoimmune condition characterized by red, well-delineated plaques with silvery scales that are usually on the extensor surfaces and scalp. "To assess the potential association between the expression of CYSLTR1 and psoriasis state, we measured CYSLTR1 levels in skin tissues obtained from both an IMQ-induced psoriasis-like murine model and normal BALB/c mice." (PMID 38617532, 2024). "However, the precise effect of CYSLTR1 on psoriasis development and the underlying mechanisms of CYSLTR1-targeted psoriasis treatment remain unclear." (PMID 38617532, 2024). "Collectively, our results strongly indicate that inhibition of CYSLTR1 signaling to target the Th17 response holds significant promise as a therapeutic approach to manage psoriasis." (PMID 38617532, 2024). "We induced psoriasis in CYSLTR1 knockout (KO) mice using IMQ to explore the role of CYSLTR1 in psoriasis development." (PMID 38617532, 2024). "IHC results showed a larger positively stained area for CYSLTR1 in both murine psoriasis model and patients, and the cell counts of CD11c+ CYSLTR1+ cells and CD3+ CYSLTR1+ cells were significantly higher in the skin lesions of patients with psoriasis." (PMID 38617532, 2024). "As montelukast exhibits substantial therapeutic benefits in the IMQ-induced psoriasis model, we next elucidated the role of CYSLTR1 in psoriasis progression." (PMID 38617532, 2024). "Given the heightened expression of CYSLTR1 in psoriatic lesions and the capacity of montelukast to restrain Th17 and IL-17, montelukast holds promise as a therapeutic agent for managing psoriasis characterized by hyperactive Th17 cells." (PMID 38617532, 2024). "We demonstrated that psoriasis can be effectively managed by blocking CYSLTR1 using topical montelukast cream and systemic administration or through genetic knockout approaches, primarily by regulating the NF-κB pathway within Th17 cells." (PMID 38617532, 2024). "Therefore, we evaluated the potential therapeutic effects of CYSLTR1 blockade in the progression of psoriasis." (PMID 38617532, 2024). "Given the remarkable therapeutic outcomes of the CYSLTR1 antagonist montelukast in the IMQ-induced psoriasis model, our initial approach involved establishing a psoriasis model in CYSLTR1 KO mice to elucidate the role of CYSLTR1 in the progression of psoriasis." (PMID 38617532, 2024). "The elevated expression of CYSLTR1 in both the skin lesions of patients with psoriasis and IMQ-induced psoriasis implies the potential involvement of CYSLTR1 in the progression of psoriasis." (PMID 38617532, 2024). "Furthermore, a notably high number of CYSLTR1-positive cells has been described in the dermal tissue of patients with psoriasis than in individuals with healthy skin, underscoring the pivotal role of leukotrienes and their receptor (CYSLTR1) in psoriasis pathogenesis." (PMID 38617532, 2024). "We demonstrated that inhibiting CYSLTR1 using montelukast sodium cream and systemic administration of montelukast sodium solution delayed disease progression in an IMQ-induced psoriasis murine model." (PMID 38617532, 2024). "Thus, blocking CYSLTR1 may be a promising strategy for psoriasis immunotherapy." (PMID 38617532, 2024).
rectal cancer (1 paper, 2023). A primary or metastatic malignant neoplasm that affects the rectum. "We observed a significant number of mutations in the CYSLTR1 and CYSLTR2 genes in CC, whereas the CYSLTR1 gene was not mutated in rectal cancer patients." (PMID 36834820, 2023).
renal carcinoma (1 paper, 2024). A carcinoma arising from the epithelium of the renal parenchyma or the renal pelvis. "RCC also demonstrates upregulation of ALOX5, TBXAS1, and cysLTR1, supporting literature on the role of TBXA2 in upregulating renal cancer and 5-LOX in progressing carcinogenesis." (PMID 39062733, 2024).
viral respiratory tract infection (1 paper, 2019). A respiratory tract infection caused by a virus. "CD49d+ CysLTR1+ (cysteinyl leukotriene receptor 1) neutrophils isolated during acute viral respiratory tract infection produced TNF, CCL2, and CCL5 and were necessary for the complete development of postviral atopic disease." (PMID 30944838, 2019).
cancer (30 papers, 2010 to 2025). A tumor composed of atypical neoplastic, often pleomorphic cells that invade other tissues. "1,4-dihydroxy quininib, a cysteinyl leukotriene receptor 1 (CysLT1) antagonist, alters UM cancer hallmarks in vitro, ex vivo and in vivo." (PMID 38341410, 2024). "We also analyzed the expression of CysLT receptor 1 (CysLTR1) in normal bile ducts and cancer sites using surgical specimens from patients with biliary tract cancer." (PMID 39064957, 2024). "Of the 10 CCA surgical specimens analyzed, 7 showed strong CysLTR1 expression at the carcinoma site." (PMID 39064957, 2024). "In cancer tissue, CYSLTR1 showed a decrease to 0.26-fold in mRNA levels compared to control with statistical significance (p < 0.05)." (PMID 27475906, 2016). "Receptors for eicosanoids in PRN and PRT cancer models are primarily located in immune cells and fibroblasts: Fpr2 is located in granulocytes, Cysltr1 and Ptger4 in macrophages (and B cells in PRT), Ptger3 in fibroblasts, while Ptgir is found in smooth muscle cells." (PMID 37386128, 2023). "Increased CysLTR1 expression has been reported in many forms of cancer, including RCC." (PMID 35408930, 2022). "CYSLTR1 and PTGER4 are primarily expressed by immune cells in human cancers, while LTB4R, PTGER1 and PTGER3 are found in neuroendocrine and tuft cells." (PMID 37386128, 2023). "IRS of LTB4R2, CYSLTR1 and CYSLTR2 receptors were medium in cancer tissue but low in normal epithelium of cancer patients and control basal stratum." (PMID 27475906, 2016). "The methylation profile for CYSLTR1 genes was used only to establish lung function in asthmatic individuals exposed to traffic-related air pollution and not for any cancer." (PMID 36834820, 2023). "With respect to CYSLTR1 expression, cancer tissue displayed a significant up-regulation compared to non-transformed squamous epithelium of cancer patients (p < 0.05) but not to control epithelium of dyspeptic patients." (PMID 27475906, 2016). "For CYSLTR1, nuclear receptor staining was also detected in 14/19 ESCC (74 %) as well as in 12/15 non-transformed mucosa specimen of patients with cancer (80 %) and 6/9 in control (66 %)." (PMID 27475906, 2016). "The observed discordance between CYSLTR1, CYSLTR2 protein expression and gene transcription can be explained by the presence of leukotriene receptor positive inflammatory cells infiltrating transformed and non-transformed tissue of cancer patients." (PMID 27475906, 2016).
tumor (24 papers, 2010 to 2025). "The cysteinyl leukotriene receptor 1 (CysLT1-R) is overexpressed in various tumor types, and its pharmacological blockade has shown antitumor effects in several preclinical models." (PMID 41353847, 2025). "CYSLTR1 expression was significantly upregulated in CRC tumor tissues compared with matched normal tissues (p = 0.0004, paired t-test)." (PMID 36834820, 2023). "In tumor samples, CYSLTR1 was significantly upregulated, but the opposite was true for CYSLTR2 expression." (PMID 36834820, 2023). "CDH1 and VIM gene expression were significantly reduced and increased, respectively, in tumor samples with high CYSLTR1 gene expression." (PMID 36834820, 2023). "The differentially upregulated genes between tumor and metastatic samples were uniformly expressed in the high-CYSLTR1 group." (PMID 36834820, 2023). "Primary tumor tissues showed significant CYSLTR1 upregulation compared with matched normal tissues, whereas it was the opposite for the CYSLTR2." (PMID 36834820, 2023). "The M values of the CpG probes for CYSLTR1 are significantly lower in primary tumor and metastasis samples than in matched normal samples, but those for CYSLTR2 are significantly higher." (PMID 36834820, 2023). "There was a significant correlation between the mRNA expression of the EMT (epithelial–mesenchymal transition) markers CDH1 (E-cadherin) and VIM (vimentin) and high CYSLTR1 gene expression in tumor samples." (PMID 36834820, 2023). "Next, we examined the mRNA expression of BDNF and CYSLTR1 in tumor and its matched normal tissue samples from CRC patients and the qRT-PCR analysis significantly showed upregulation in tumor samples compared to its normal tissue samples for both genes." (PMID 34771682, 2021). "The ROC analysis result was also convincing in TCGA-COAD dataset and the best fit multivariate Cox models using CD66b, BDNF, CYSLTR1 expression in tumor tissues and the significant clinical factors (age, LNM and TNM) was achieving high AUC values (AUC = 0.73)." (PMID 34771682, 2021). "According to functional studies, CYSLTR1 mediates preferentially pro-carcinogenic effects, whereas CYSLTR2 has been associated with anti-tumor mechanisms." (PMID 27475906, 2016). "Furthermore, positive ERα expression correlated with increased levels of the G-protein coupled cysteinyl leukotriene receptor 1 (CysLT1R) and nuclear β-catenin, both known tumour promoters." (PMID 38549115, 2024). "CYSLTR1 gene expression was significantly high in tumor and metastasis samples, and the 105 common upregulated genes were also significantly high in these groups; hence, the expression of these genes was positively correlated with CYSLTR1 expression." (PMID 36834820, 2023). "This suggests that tumour infiltrate may contribute to high CYSLTR1 expression in UM patients with reduced survival." (PMID 33066024, 2020). "Furthermore, in double-mutant Cysltr1-/-/ApcMin/+ mice, a significant reduction of the tumor burden was observed compared to control littermates, and this effect was accompanied with decreased systemic inflammation indicated by PGE2 levels." (PMID 28402256, 2017). "Moreover, the Cysltr1−/− polyps had a significantly decreased tumor infiltration of F4/80-positive macrophages compared to those of the wild-type mice." (PMID 28410235, 2017). "CYSLTR1 and CYSLTR2 expression were significantly differentially regulated between CRC tumor tissues and corresponding normal tissues in the TCGA-COADREAD cohort." (PMID 36834820, 2023). "The CYSLTR1 and CYSLTR2 gene expressions gradually increased and decreased in stage II, III and IV primary tumor samples, respectively." (PMID 36834820, 2023). "Hence, CYSLTR1 and CYSLTR2 expression influenced tumor metastasis through the alteration of EMT marker expression (CDH1 and VIM)." (PMID 36834820, 2023).
tumor (continued). "We validated our finding using 24 paired normal and tumor tissue samples and found significantly elevated CD274 mRNA expression in the tumor tissues compared to the corresponding normal tissues; this pattern was also observed for CYSLTR1 mRNA expression." (PMID 37316937, 2023). "The CYSLTR1 and CYSLTR2 gene expressions and methylation were validated in an additional in silico cohort (E-MTAB), with the transcriptome and genome-wide methylation sequencing for primary tumor and normal samples." (PMID 36834820, 2023). "Interestingly, CDH1 expression was lower and VIM expression was higher in the tumor samples with high CYSLTR1 expression, although the statistical significance was not achieved, possibly due to the smaller number of patients." (PMID 36834820, 2023).
infection (7 papers, 2009 to 2024). The state of being infected such as from the introduction of a foreign agent such as serum, vaccine, antigenic substance or organism. "We verified that susceptible mice secreted higher levels of LTs and LXs than resistant mice, and only the former strain developed a less severe early infection when CysLTR1 was blocked." (PMID 26635449, 2015). "Indeed, the low influx of PMN cells to the site of infection and the decreased production of TNF-α and IL-12 associated with enhanced production of IL-10 detected 48 h after infection of MLT-treated B10.A mice indicated a prevalent LX signaling when CysLTR1 was blocked." (PMID 26635449, 2015).
inflammation (6 papers, 2013 to 2025). Aberrant reaction of the microcirculation characterized by movement of fluid and leukocytes from the blood into extravascular tissues. "CYSLTR1 is predominantly expressed in airway smooth muscle cells, mast cells, eosinophils, monocytes, and macrophages, mediating chronic airway inflammation and tissue damage through bronchoconstriction, increased vascular permeability, and inflammatory cell infiltration." (PMID 40444276, 2025).
colon polyps (3 papers, 2017 to 2025). "Animal experiments showed that AOM/DSS model mice had low-grade atypical hyperplasia of colon polyps and reduced inflammation levels in the Cysltr1-/- group compared with the wild-type group, supporting the important role of CysLTR1 in colon tumorigenesis." (PMID 41210682, 2025). "We found that AOM/DSS female mice with a global disruption of the Cysltr1 gene (Cysltr1−/−) had a higher relative body weight, a more normal weight/length colon ratio and smaller-sized colonic polyps compared to AOM/DSS wild-type counterparts." (PMID 28410235, 2017). "The Cysltr1−/− colonic polyps exhibited significant decreases in nuclear β-catenin and COX-2 protein expression, while the normal crypts surrounding the polyps exhibited increased Mucin 2 expression." (PMID 28410235, 2017). "The AOM/DSS Cysltr1−/− mice mainly exhibited colonic polyps of <1 mm in diameter with no polyps exceeding 1.5 mm, while the wild-type (Cysltr1+/+) counterparts exhibited all sizes of polyps, including polyps exceeding 1.5 mm in size." (PMID 28410235, 2017).
cardiovascular diseases (2 papers, 2020 to 2025). "While CysLTR2 is generally considered to have a more prominent role in the cardiovascular system due to its high expression in the heart, it is increasingly recognized that both CysLTR1 and CysLTR2 play important but distinct roles in cardiovascular diseases." (PMID 41488008, 2025).
CYSLTR1 also shares sentences with these, for which no sentence is quoted: colitis (5 papers); renal cell carcinoma (5); lung carcinoma (4); neuroblastoma (4); testicular cancer (4); Allergy (3); atherosclerosis (3); bladder cancer (3); colorectal adenocarcinoma (3); epidermoid carcinoma (3); gastric cancer (3); respiratory disease (3); transitional cell carcinoma (3); adenocarcinoma (2); allergic asthma (2); Alzheimer disease (2); amyloidosis (2); astrocytoma (2); breast tumor (2); cardiac ischemia (2); chronic rhinosinusitis (2); experimental autoimmune encephalomyelitis (2); lung fibrosis (2); metastatic disease (2); Parkinson disease (2); rheumatoid arthritis (2); acute respiratory distress syndrome (1); acute respiratory failure (1); B-cell lymphoma (1); bacterial infections (1).
A further 47 diseases each share a sentence with CYSLTR1 in 1 paper.